AMN (amnion associated transmembrane protein)
Description:
Membrane-bound component of the endocytic receptor formed by AMN and CUBN. Required for normal CUBN glycosylation and trafficking to the cell surface. The complex formed by AMN and CUBN is required for efficient absorption of vitamin B12. Required for normal CUBN-mediated protein transport in the kidney (Probable).
Synonyms: amnionless; IGS2; PRO1028
Tractability: Antibody: UniProt places it where antibodies can reach, with high confidence; its Gene Ontology location is reachable by antibodies, with high confidence; UniProt predicts a signal peptide or a membrane-spanning region.
Gene: Protein-coding gene on chromosome 14 (102,922,663 to 102,933,596, forward strand). Ensembl gene ENSG00000166126.
Subcellular location: Apical cell membrane (Isoform 1); Cell membrane; Endosome membrane; Membrane, coated pit; Secreted (Soluble protein amnionless)
Pathways (Reactome):
Disease: Defective AMN causes MGA1; Defective CUBN causes MGA1
Metabolism: Uptake of dietary cobalamins into enterocytes
Transport of small molecules: HDL clearance
Gene Ontology:
Molecular function: cargo receptor activity; protein binding; signaling receptor binding
Biological process: cobalamin metabolic process; cobalamin transport; Golgi to plasma membrane protein transport; receptor-mediated endocytosis; intracellular protein localization; renal protein absorption
Cellular component: apical plasma membrane; endocytic vesicle; extracellular exosome; extracellular region; membrane; microvillus membrane; plasma membrane; receptor complex; apical part of cell; brush border membrane; endosome membrane; protein-containing complex
Genetic constraint (gnomAD): Loss-of-function variants: 40 observed, 36 expected, observed/expected ratio (o/e) 1.11, 90% interval 0.86 to 1.45. The synonymous counts are far from expectation, so gnomAD's model fits this gene poorly and the ratio says little. Missense variants: 701 observed, 528.95 expected, observed/expected ratio (o/e) 1.33, 90% interval 1.25 to 1.41. Synonymous variants: 380 observed, 259.62 expected, observed/expected ratio (o/e) 1.46, 90% interval 1.35 to 1.59.
Homologues: Orthologues: chimpanzee AMN (99% identical), macaque AMN (77% identical), pig AMN (74% identical), dog AMN (66% identical), mouse Amn (66% identical), rat Amn (65% identical), guinea pig AMN (61% identical), tropical clawed frog amn (37% identical), zebrafish amn (36% identical), Drosophila melanogaster Amnionless (19% identical).
Diseases named in the same sentence as AMN in open-access papers:
AMN is named in the same sentence as 21 diseases in open-access papers, as found by Europe PMC text mining. Sharing a sentence is not in itself a finding about the gene and the disease. The quoted sentences say what the papers report.
megaloblastic anemia (5 papers, 2006 to 2024). Anemia characterized by the presence of unusually large erythroblasts in the bone marrow called megaloblasts. "Cubilin(encoded by CUBN), amnionless(encoded by AMN), and megalin form a multiligand receptor complex; CUBN or AMN gene variants have been implicated as a hereditary cause of megaloblastic anemia, proteinuria, and neurological impairment." (PMID 38992620, 2024). "Due to the combination of megaloblastic anemia, vitB12 deficiency and proteinuria, screening for abnormalities in the AMN and CUBN gene was performed." (PMID 37710296, 2023). "IGS, a rare autosomal recessive disorder caused by mutations in cubilin (CUBN) and/or amnionless (AMN), was first characterized in the 1960s and results in megaloblastic anemia during childhood as a result of selective malabsorption of Vitamin B12." (PMID 25147783, 2014).
Imerslund-Gräsbeck Syndrome (4 papers, 2012 to 2024). "Using targeted Sanger sequencing of AMN and CUBN, we identified novel compound heterozygous mutations in AMN in a family from the United Kingdom with typical clinical features of Imerslund-Gräsbeck Syndrome." (PMID 26040326, 2015). "We have identified novel compound heterozygous mutations in AMN in a family from the United Kingdom with clinical features of Imerslund-Gräsbeck Syndrome." (PMID 26040326, 2015). "Recessive mutations in CUBN or AMN cause Imerslund-Gräsbeck Syndrome (IGS), while recessive mutations in GIF cause Intrinsic Factor Deficiency (IFD)." (PMID 22929189, 2012).
acute kidney injury (1 paper, 2022). Sudden and sustained deterioration of the kidney function characterized by decreased glomerular filtration rate, increased serum creatinine or oliguria. "Additionally, in vivo experiments further confirmed that the reduced expression of renal Cubilin did not cause abnormal cytoplasmic localization of AMN in the mice model of LPS-induced acute kidney injury and Adriamycin-induced nephropathy with GFB impairment." (PMID 36266725, 2022).
anaemia (1 paper, 2018). "Mutations in either cubilin (CUBN) or amnionless (AMN) genes cause Imerslund–Gräsbeck syndrome (IGS), a hereditary disease characterised by anaemia attributed to selective intestinal malabsorption of cobalamin and low-molecular weight proteinuria." (PMID 29402915, 2018).
asthma (1 paper, 2022). "The SNP rs12436181 (near genes TRAF3, AMN) was associated with childhood-onset asthma, eczema, body size at age 10 years, and weight in the Open Targets Genetics20." (PMID 36253437, 2022).
depression (1 paper, 2023). "While its direct involvement in the development of depression or BC is not known, this SNP interacts with several genes that have already been reported (i.e., TRAF3 and RCOR1), or that could play a role in the pathogenesis of the two traits (i.e., AMN, ANKRD9, and MIR4309)." (PMID 37143087, 2023).
Hypertension (1 paper, 2025). The presence of chronic increased pressure in the systemic arterial system. "Among tissues linked to hypertension, PPP1R14D (Z = 3.12) and AMN (Z = 2.12) show maximal expression in kidney cortex, while PTMAP9 (Z = 1.16), RRAGA (Z = 1.37) and CREB1 (Z = 1.21) are most abundant in the aorta." (PMID 40909129, 2025).
metabolic syndrome (1 paper, 2025). A cluster of metabolic risk factors for CARDIOVASCULAR DISEASES and TYPE 2 DIABETES MELLITUS. "Given AMN’s central role in metabolic regulation, it is closely associated with metabolic syndrome, a major risk factor for ED." (PMID 40529500, 2025).
nephropathic cystinosis (1 paper, 2020). An autosomal recessive condition caused by mutation(s) in the CTNS gene, encoding cystinosin. "Besides CLCN5 (DD1) and OCRL (Lowe syndrome and Dent disease type 2) genes, they include LRP2 (DB/FOAR), CUBN, AMN (Imerslund–Gräsbeck syndrome), and CTNS (nephropathic cystinosis)." (PMID 31947599, 2020).
psychosis (1 paper, 2012). "One IGS case (MGA12) with mutations in AMN showed severe psychosis, which only responded to high-dose Cbl therapy." (PMID 22929189, 2012).
cancer (5 papers, 2020 to 2026). A tumor composed of atypical neoplastic, often pleomorphic cells that invade other tissues. "Encoding a transmembrane protein named amnionless, AMN is involved in the plasma membrane transport of Cubilin, and may influence cancer progression through the Cubilin-FGF8 (fibroblast growth factor 8) interaction." (PMID 37143087, 2023).
AMN also shares sentences with these, for which no sentence is quoted: tumor (3 papers); Chilton-Okur-Chung neurodevelopmental syndrome (1); eczema (1); Encephalopathy (1); hypocobalaminemia (1); Imerslund-Grasbeck syndrome 2 (1); infection (1); Nephropathy (1); Obesity (1); type 2 diabetes (1).